COL4A1 (collagen type IV alpha 1 chain)
Description:
Type IV collagen is the major structural component of glomerular basement membranes (GBM), forming a 'chicken-wire' meshwork together with laminins, proteoglycans and entactin/nidogen. Arresten, comprising the C-terminal NC1 domain, inhibits angiogenesis and tumor formation. The C-terminal half is found to possess the anti-angiogenic activity. Specifically inhibits endothelial cell proliferation, migration and tube formation.
Synonyms: BSVD; BSVD1; COL4A1s; PADMAL; RATOR
Tractability: Antibody: its Gene Ontology location is reachable by antibodies, with high confidence; UniProt places it where antibodies can reach, with medium confidence; UniProt predicts a signal peptide or a membrane-spanning region. Other modalities: an approved drug acts on it.
Gene: Protein-coding gene on chromosome 13 (110,148,963 to 110,307,202, reverse strand). Ensembl gene ENSG00000187498.
Subcellular location: Secreted, extracellular space, extracellular matrix, basement membrane
Pathways (Reactome):
Extracellular matrix organization: Anchoring fibril formation; Assembly of collagen fibrils and other multimeric structures; Collagen biosynthesis and modifying enzymes; Collagen chain trimerization; Collagen degradation; Crosslinking of collagen fibrils; ECM proteoglycans; Fibronectin matrix formation; Integrin cell surface interactions; Laminin interactions; Non-integrin membrane-ECM interactions
Developmental Biology: NCAM1 interactions
Disease: Attachment of bacteria to epithelial cells
Signal Transduction: Signaling by PDGF
Vesicle-mediated transport: Scavenging by Class A Receptors
Gene Ontology:
Molecular function: extracellular matrix structural constituent; extracellular matrix structural constituent conferring tensile strength; platelet-derived growth factor binding; protein binding
Biological process: basement membrane organization; blood vessel morphogenesis; brain development; branching involved in blood vessel morphogenesis; renal tubule morphogenesis; retinal blood vessel morphogenesis; collagen fibril organization; extracellular matrix organization; epithelial cell differentiation
Cellular component: collagen type IV trimer; extracellular matrix; basement membrane; endoplasmic reticulum lumen; extracellular region; collagen trimer
Genetic constraint (gnomAD): Loss-of-function variants: 40 observed, 218.84 expected, observed/expected ratio (o/e) 0.18, 90% interval 0.14 to 0.24. The upper end of that interval is the gene's LOEUF score, 0.24, which puts it in group 1 of 6, group 1 being the genes least tolerant of losing a copy. Missense variants: 1,618 observed, 2,268.5 expected, observed/expected ratio (o/e) 0.71, 90% interval 0.68 to 0.74. Synonymous variants: 836 observed, 831.68 expected, observed/expected ratio (o/e) 1.01, 90% interval 0.95 to 1.06.
Gene-disease validity (ClinGen):
ClinGen rates the evidence that COL4A1 causes each of these diseases.
COL4A1-related disorder (autosomal dominant): Definitive.
Homologues: Orthologues: chimpanzee COL4A1 (99% identical), macaque COL4A1 (98% identical), dog COL4A1 (92% identical), rat Col4a1 (91% identical), mouse Col4a1 (91% identical), rabbit COL4A1 (90% identical), guinea pig COL4A1 (89% identical), pig COL4A1 (83% identical), tropical clawed frog col4a1 (65% identical), zebrafish col4a1 (60% identical). Paralogues in human: COL4A5 (61% identical), COL4A3 (52% identical), COL4A6 (48% identical), COL4A2 (48% identical), COL4A4 (40% identical), COL7A1 (37% identical), COL5A1 (36% identical), COL11A1 (35% identical), COL11A2 (34% identical), COL5A3 (34% identical), COL2A1 (34% identical), COL1A1 (33% identical), and 25 more.
Diseases named in the same sentence as COL4A1 in open-access papers:
COL4A1 is named in the same sentence as 341 diseases in open-access papers, as found by Europe PMC text mining. Sharing a sentence is not in itself a finding about the gene and the disease. The quoted sentences say what the papers report.
gastric cancer (28 papers, 2009 to 2025). A primary or metastatic malignant neoplasm involving the stomach. "COL4A1 is associated with gastric cancer peritoneal metastasis through weighted gene co-expression network analysis and clinical specimen validation." (PMID 40535808, 2025). "In addition, we identified three key mRNAs (CD93, COL3A1 and COL4A1) associated with gastric cancer peritoneal metastasis through WGCNA analysis and clinical specimen validation." (PMID 36690975, 2023). "Additionally, COL4A1 has been implicated in trastuzumab resistance in gastric cancer, potentially conferring resistance to this targeted therapy." (PMID 38041130, 2023). "Our observed upregulation of CTNNB1 and COL4A1 is consistent with earlier studies reporting elevated expression of these genes in gastric cancer tissues, particularly in the presence of H. pylori infection." (PMID 41291892, 2025). "COL4A1 also demonstrated elevated expression in gastric cancer tissues, while normal samples showed minimal staining." (PMID 41291892, 2025). "This emphasizes our contribution in extending the understanding of COL4A1 as a critical regulator in gastric cancer progression, particularly in the context of H. pylori-associated malignancy." (PMID 41291892, 2025). "Concurrently, substantial evidence indicates that extracellular matrix remodelling genes such as COL4A1 play critical roles in gastric cancer invasion and progression, linking matrix alterations with H. pylori induced oncogenic processes." (PMID 41291892, 2025). "The GO term pathway analysis results show that ECM-associated pathways and their members, COL4A1, PXDN, and TGFBI, are involved in gastric cancer’s acquired drug resistance mechanism." (PMID 38968283, 2024). "COL4A1 shows overexpression in gastric cancer tissues and is upregulated in trastuzumab-resistant gastric cancer cells." (PMID 38968283, 2024). "Initially, we developed a gene signature related to lactylation to forecast the outcome of stomach cancer by analyzing genes with varying expressions, such as COL4A1, SLC16A7, and IRAK1." (PMID 39669362, 2024). "COL4A1 has been considered a crucial marker to drive trastuzumab resistance in gastric cancer by performing protein/gene interactions and biological process annotation analyses." (PMID 38968283, 2024). "Intriguingly, lnc-TRIM28-14 was positively correlated with the expression levels of CD93 and COL4A1 in gastric cancer peritoneal metastasis, suggesting a regulatory relationship between them." (PMID 36690975, 2023). "In silico studies have shed light on the potential of COL4A1 in conferring trastuzumab resistance and promoting gastric carcinoma recurrence." (PMID 38041130, 2023). "In gastric cancer, COL4A1 overexpression is related to trastuzumab resistance and tumor recurrence, leading to poor patient outcomes." (PMID 35455650, 2022). "COL4A1 overexpression has previously been shown to be correlated with overall survival in gastric cancer; it was correlated with IGFBP7 with p = 6.99147E-33 in our study." (PMID 34745945, 2021). "Hub genes of COL1A1, COL4A1, COL12A1, and PDGFRB were overlapped in both PPI hub gene list and the turquoise module with significant association with the prognosis in gastric cancer." (PMID 35111208, 2021). "And it has been reported that COL4A1 plays a key role in the recurrence of multiple tumors, such as gastric carcinoma and bladder cancer." (PMID 35046992, 2021). "These possibilities point toward a future in which molecularly informed treatment plans, centered on targets such as CTNNB1 and COL4A1, may offer improved outcomes for patients with H. pylori–related gastric cancer." (PMID 41291892, 2025). "Additionally, it was reported that miR–124 inhibits the epithelial–mesenchymal transition in gastric cancer cells via its target COL4A1." (PMID 38922066, 2024).
gastric cancer (continued). "Moreover, there was a positive correlation between lnc-TRIM28-14 and the expression of CD93 and COL4A1 in gastric cancer peritoneal metastasis, suggesting a regulatory relationship between them." (PMID 36690975, 2023). "Furthermore, in microarray-based datasets of gliomas, pancreatic tumors, melanomas, and gastric cancers, we identified a correlation between the poor survival rates of the four patient groups and high expression levels of COL4A1." (PMID 35455650, 2022). "Moreover, it was further testified that COL4A1 silence exhibited its inhibitory effects on gastric cancer cells via blocking Hedgehog signaling pathway." (PMID 35297303, 2022). "In another example, COL4A1 may confer trastuzumab resistance and promote gastric carcinoma recurrence in GC 45,46." (PMID 33976737, 2021). "Several collagen genes were found to be overexpressed in gastric cancer and, among these, COL1A1 and COL4A1 were closely associated with overall survival of gastric cancer patients and could be regarded as risk factors for poor prognosis." (PMID 32046329, 2020). "Additionally, research suggested that COL4A1's activation of the PI3K/AKT pathway may result in the recurrence of gastric cancer." (PMID 37488671, 2023). "In addition, miR-124 can target COL4A1 and inhibit the epithelial-mesenchymal transition (EMT) caused by TGF-β1 in GC, thereby inhibiting the development of gastric cancer." (PMID 40296904, 2025). "Protein-level validation using immunohistochemistry (IHC) data from the HPA database revealed that THBS2, CTNNB1, COL4A1, and E2F3 exhibited markedly higher staining intensity in gastric cancer tissues compared to normal gastric mucosa." (PMID 41291892, 2025). "Our analysis identified hsa-miR-9-3p and hsa-miR-9-5p as shared regulators of COL4A1, CTNNB1, THBS2, and E2F3, a pattern that aligns partially with earlier studies reporting dysregulation of the miR-9 family in gastric cancer." (PMID 41291892, 2025). "COL4A1 silence hampers the invasion, migration and epithelial-mesenchymal transition (EMT) of gastric cancer cells." (PMID 39044041, 2024). "Consistently, the protein level of COL4A1 was elevated, whereas the protein level of COL4A2 was reduced in the gastric cancer cell lines." (PMID 38907304, 2024). "Here, we combined patient clinicopathological data with COL4A1, SLC16A7 and IRAK1 to create a predictive nomogram for gastric cancer." (PMID 39669362, 2024). "A previous study showed that seven collagen genes (COL1A2, COL4A1, COL6A2, COC6A1, COL4A2, and COL11A1) were highly expressed in gastric cancer tissues, consistent with our findings." (PMID 39220121, 2024). "Through GEPIA database, we found that COL1A1, COL4A1 and COL12A1 were differentially expressed in patients with gastric cancer, significantly suggesting a poor prognosis." (PMID 37700383, 2023). "Through GEPIA database, we found that COL1A1, COL4A1 and COL12A1 was differentially expressed in patients with gastric cancer, significantly suggesting a poor prognosis." (PMID 37700383, 2023). "In this study, we performed whole-transcriptome sequencing on tissue samples of gastric cancer peritoneal metastasis, and identified GCPM-related lncRNAs (lnc-RFNG-1 and lnc-TRIM28-14) and mRNAs (CD93, COL3A1, and COL4A1)." (PMID 36690975, 2023). "COL4A1, SLC16A7 or IRAK1 are prognostic biomarkers in gastric cancer." (PMID 39669362, 2024). "We suggest that suppression and/or induction of COL4A1, PXDN and TGFBI and their molecular interplays enriched in the extracellular-related pathways may provide crucial clues to enhance gastric cancer’s chemosensitivity." (PMID 38968283, 2024). "We suggest that suppression and/or induction of COL4A1, PXDN, and TGFBI, and their molecular interplays involved in the ECM-related pathways may provide crucial clues to enhance the chemosensitivity of gastric cancer." (PMID 38968283, 2024).
gastric cancer (continued). "In addition, COL4A1 was upregulated not only in HCC but also in most types of cancer, including colorectal cancer, gastric cancer as well as head and neck cancer, etc.." (PMID 32746865, 2020). "COL4A1 is not specific for gastric cancer, investigation such genes can provide a better understanding of other cancers." (PMID 30430424, 2019). "Moreover, recent resistance profiling in gastric cancer has suggested that Wnt beta catenin activation and ECM remodeling cooperate to generate a drug tolerant state, which aligns with our findings for CTNNB1 and COL4A1." (PMID 41291892, 2025). "Functional validation using siRNA-mediated knockdown in MNK45 and AGS cell lines demonstrated that COL4A1 and CTNNB1 play essential roles in maintaining tumor cell proliferation, clonogenic survival, and migratory potential, confirming their functional importance in gastric cancer progression." (PMID 41291892, 2025). "Our results suggest that the suppression and/or induction of COL4A1, PXDN and TGFBI and their molecular interplays enriched in the Extracellular-related pathways may provide crucial clues to enhance the chemosensitivity of gastric cancer." (PMID 38968283, 2024). "Although previous studies have identified COL4A1 as a key gene in the development, progression and recurrence of gastric cancer and testified that COL4A1 was concerned with its poor prognosis, the molecular mechanism of COL4A1 in gastric cancer progression has not been elucidated." (PMID 35297303, 2022). "Our GO term pathway analysis results strongly suggest that suppression and/or induction of COL4A1, PXDN and TGFBI and their molecular interplays involved in the extracellular-related pathways may provide crucial clues to enhance the chemosensitivity of gastric cancer." (PMID 38968283, 2024). "In the same way, we found that COL4A1 silence downregulated the expressions of Ki67, PCNA, MMP2, MMP9, N-cadherin and Vimentin but promoted E-cadherin expression in MKN-45 cells, revealing that COL4A1 silence could help to suppress the proliferation, metastasis and EMT in gastric cancer." (PMID 35297303, 2022).
Nephropathy (28 papers, 2011 to 2026). A nonspecific term referring to disease or damage of the kidneys. "Mutations in the COL4A1 gene contribute to a broad spectrum of disorders involving a specific phenotype comprising hereditary angiopathy, nephropathy, aneurysms, and cramps (HANAC)." (PMID 35401403, 2022). "We show that Col4a1 mutations in mice cause hypotension and renal disease, including proteinuria and defects in Bowman's capsule and the glomerular basement membrane, indicating a role for Col4a1 in glomerular filtration." (PMID 26839400, 2016). "In conclusion, Col4a1 mutations cause renal disease that involves cell-specific disease mechanisms, including ER stress and BM defects." (PMID 26839400, 2016). "Noteworthy, PKD is a recognized phenotypic trait of HANAC (hereditary angiopathy, nephropathy, aneurysms, and muscle cramps) syndrome, an autosomal dominant disorder determined by heterozygous pathogenetic variants in the COL4A1 (Collagen, Type IV, α-1; MIM: 120130) gene." (PMID 38790225, 2024). "There are nephrotic manifestations of human COL4A1 mutations of the Hereditary Angiopathy, Nephropathy, Aneurysms, and Muscle Cramps (HANAC) syndrome and recent research revealed glomerular hyperpermeability and adult onset glomerulocystic kidney disease in association with COL4A1 mutations." (PMID 29651426, 2018). "Pathogenic mutations of COL4A1 are associated with neurological, vascular and renal disorders." (PMID 27190376, 2016). "Our analysis of the development and progression of renal disease caused by Col4a1 mutations has expanded the spectrum of potential clinical defects that can develop in humans with COL4A1 mutations and identified the importance of α1α1α2(IV) in adult kidney function and pathophysiology." (PMID 26839400, 2016). "In summary, we present a novel COL4A1 mutation linked with kidney disease that is predicted to cause loss of a highly conserved part of the C-terminal NC1 domain of the α1 type IV collagen chain that is important in interactions within and between type IV collagen heterotrimers." (PMID 27190376, 2016). "Our findings extend the spectrum of COL4A1 mutations linked with renal disease and demonstrate that the highly conserved C-terminal part of the NC1 domain of the α1 chain of type IV collagen is important in the integrity of glomerular basement membrane in humans." (PMID 27190376, 2016). "We conclude that the COL4A1 mutation is responsible for the familial renal disease in this kindred." (PMID 27190376, 2016). "For instance, in HANAC (hereditary angiopathy, nephropathy, aneurysms, and muscle cramps) syndrome, caused by COL4A1 variations, patients often present with multicystic kidneys, suggesting that the pathogenic effects may involve defective cell–basement membrane interactions." (PMID 40565535, 2025). "Extracentral nervous system manifestations, particularly ocular abnormalities and renal disease, were predominantly seen in COL4A1-related disease." (PMID 42099677, 2026). "Variations in COL4A1 have been associated with HANAC (hereditary angiopathy, nephropathy, aneurysms, and muscle cramps) syndrome, which can present nephropathy and renal cysts." (PMID 40565535, 2025). "Variations in the genes that encode these α chains—especially COL4A1, COL4A3, COL4A4, and COL4A5—have been associated with several kidney disorders, which involve not only glomerular dysfunction but also the formation of cysts." (PMID 40565535, 2025). "Using a lower threshold (p < 0.05), genes previously linked to kidney disease (TINAG and COL4A1) were found among common risk genes." (PMID 38767678, 2024). "Due to the relatively high sequence variability within this gene, attempts have been made to link COL4A1 SNPs to cardiovascular or kidney diseases, among other conditions." (PMID 37373172, 2023).